CTCF (CCCTC-binding factor)
Diseases named in the same sentence as CTCF in open-access papers (continued):
Sharing a sentence is not in itself a finding about the gene and the disease.
acute lymphoblastic leukemia (13 papers, 2014 to 2026). Leukemia with an acute onset, characterized by the presence of lymphoblasts in the bone marrow and the peripheral blood. "Heterozygous, loss-of-function mutations of key architectural factors, such as CTCF and various subunits of the cohesin complex, are frequently detected in myeloid and lymphoblastic leukemia." (PMID 34054841, 2021). "Isolated CTCF mutations have been identified in breast, prostate and Wilms’ tumours and acute lymphoblastic leukaemia." (PMID 30513694, 2018). "Silencing of CTCF in the RS4;11 acute lymphoblastic leukaemia cell line increased colony numbers in soft agar overlays compared to control, though CTCF protein appeared to be reduced to minimal levels." (PMID 30513694, 2018). "Proteogenomic analyses on ETV6/RUNX1-positive, hyperdiploid pediatric acute lymphoblastic leukemia samples showed underexpression of CCCTC-binding factor (CTCF) and cohesins, master regulators of chromatin architecture, suggesting a potential mechanism for dysregulating gene expression." (PMID 37738504, 2024). "In addition to the clinical samples, we further determined the expression features of CTCF in various human lymphoblastic leukemia cell lines." (PMID 24393203, 2014). "However, the loss of CTCF and consequently TAD fusion occurred in T-ALL (acute lymphoblastic leukemia), resulting in the establishment of spatial interactions between MYC and super-enhancer and the up-regulation of MYC." (PMID 35580989, 2022). "Our study in the acute lymphoblastic leukemia cell line SEM showed deletions to ZF1 and ZF10 resulted in moderate changes to CTCF binding and dysregulated transcription of a subset of genes regulated by CTCF." (PMID 40355969, 2025). "In T‐cell acute lymphoblastic leukemia (T‐ALL), a deletion of the boundary between the TAL1‐ and STIL loci disrupts a CTCF site, placing the TAL1 oncogene under control of an enhancer outside its neighborhood." (PMID 39853740, 2026).
ovarian carcinoma (13 papers, 2013 to 2024). A malignant neoplasm originating from the surface ovarian epithelium. "In order to further understand the roles of RPL35A and CTCF in ovarian cancer cells, a sequence of assays involving loss/gain of their function were conducted both in vitro and in vivo." (PMID 38436544, 2024). "To investigate the underlying mechanisms whereby CTCF influences ovarian cancer metastasis, we used PCR-array analysis to compare the gene expression profiles of shCTCF1-transfected and control vector-transfected cancer cells (SKOV3 and A2780)." (PMID 28977939, 2017). "In summary, we demonstrated that CTCF is overexpressed in ovarian cancer and is associated with a poor prognosis in ovarian cancer patients." (PMID 28977939, 2017). "In conclusion, elevated IGF2 expression in epithelial ovarian cancers is associated with increased methylation of a novel regulatory sequence motif that we have shown binds to the CTCF protein." (PMID 23745176, 2013). "Consistent with this hypothesis, we found that CTCF promoted cell migration and invasion in ovarian cancer in vitro and in vivo by loss-of-function studies." (PMID 28977939, 2017). "Mechanically, RPL35A promoted the direct binding of transcription factor YY1 to CTCF in ovarian cancer cells." (PMID 38436544, 2024). "More specifically, RPL35A promotes the direct binding of the transcription factor YY1 to CTCF in ovarian cancer cells." (PMID 38436544, 2024). "The current study conducted Firefly luciferase & Renilla luciferase and CHIP assays, which revealed that overexpression of RPL35A facilitated the direct interaction between transcription factor YY1 and CTCF in ovarian cancer cells." (PMID 38436544, 2024). "Further, the depletion of CTCF in ovarian cancer cell lines (SKOV3 and A2780) decreased cell migration by consistently downregulating three metastasis-associated genes, including CTBP1, SRC, and SERPINE." (PMID 36589746, 2022). "The oncogene CTCFL (BORIS), the paralog of CTCF, is a transcriptional factor highly expressed in ovarian cancer (but in rarely any other tissue in females) with cancer-specific characteristics and therapeutic potential." (PMID 35132075, 2022). "Ovarian cancers exemplify the oncogenic potential of CTCF, where metastatic lesions display elevated CTCF expression." (PMID 36589746, 2022). "Using the Kaplan Meier plotter the prognostic significance of mRNA levels of CTCFL in gastric, breast, and ovarian cancer were interrogated, similarly to the respective levels of CTCF." (PMID 30275357, 2018). "The prognostic significance for survival of mRNA levels of CTCF in gastric, breast, and ovarian cancer were checked using Kaplan Meier plotter." (PMID 30275357, 2018). "In stage I and II ovarian cancer patients with a high CTCFL mRNA expression displayed a worse OS compared with counterparts with low CTCF mRNA expression (HR = 2.66, 95% CI = 1.3–5.46, p = 0.0055, not shown)." (PMID 30275357, 2018). "In stage I and II ovarian cancer patients with a high CTCF mRNA expression also displayed a worse OS compared with counterparts with low CTCF mRNA expression (HR = 1.96, 95% CI = 1.02–3.78, p = 0.039, not shown)." (PMID 30275357, 2018). "We also verified the significance of CTCF in ovarian cancer metastasis in clinical specimens and found that CTCF increased cell invasion and promoted tumor metastasis." (PMID 28977939, 2017). "Here, we report that CTCF expression was upregulated in ovarian cancer tissues and that increased CTCF expression was directly associated with poor prognosis of epithelial ovarian cancer patients." (PMID 28977939, 2017). "Noteworthy, we found that CTCF expression was inversely correlated with the 5-year overall survival rate of ovarian cancer patients (P=0.027)." (PMID 28977939, 2017). "These in vivo clinical data indicated a positive correlation between CTCF expression and ovarian cancer metastasis, further verifying our in vitro results." (PMID 28977939, 2017).
ovarian carcinoma (continued). "Accordingly, in order to further elucidate the details of the underlying mechanisms, we used ChIP-seq technology to identify the genomic locations bound by CTCF in Skov3 ovarian cancer cells." (PMID 28977939, 2017). "To further validate the significance of CTCF in ovarian cancer metastasis, we evaluated CTCF expression in primary lesions and paired metastatic lesions from a total of 12 ovarian cancer patients." (PMID 28977939, 2017). "Accordingly, we further examined the effects of CTCF knockdown on the migration and invasion of ovarian cancer cells." (PMID 28977939, 2017). "Together, these results indicate that CTCF promotes ovarian cancer progression in a cell proliferation-independent manner." (PMID 28977939, 2017). "To further study the function of CTCF in epithelial ovarian cancer progression, we transfected 2 ovarian cancer cell lines (SKOV3 and A2780) with 2 different lentiviral shRNAs." (PMID 28977939, 2017). "Western blot analysis revealed a 2-fold increase in CTCF protein expression in metastatic lesions (M) compared with primary ovarian cancer lesions (P) (N=12, P=0.0014)." (PMID 28977939, 2017). "To further evaluate the CTCF-mediated regulation of the expression of metastasis-associated genes, we analyzed the correlations between CTCF and SRC, CTBP1 and SERPINE1 gene expression in 255 human ovarian cancer specimens obtained from the GSE13876 database." (PMID 28977939, 2017). "More importantly, we found that CTCF expression was an indicator of poor prognosis in ovarian cancer patients." (PMID 28977939, 2017). "Together, these data strongly suggest that CTCF mediates ovarian cancer metastasis by regulating the expression of metastasis-associated genes, including CTBP1, SERPINE1 and SRC." (PMID 28977939, 2017). "In the current study, we observed an increase in CTCF mRNA and protein expression in human epithelial ovarian cancer tissues compared with paired normal tissues in 3 cohorts of patients." (PMID 28977939, 2017). "More importantly, CTCF expression was higher in metastatic lesions compared to primary tumors from the same ovarian cancer patients." (PMID 28977939, 2017). "High expression level of BORIS determined by immunohistochemistry and high BORIS/CTCF mRNA ratio are related to poorer prognosis for patients with esophageal cancer and epithelial ovarian cancer, respectively." (PMID 26849232, 2016). "We confirmed binding of CTCF to this region in ovarian cancer cells, as well as the paralog of CTCF, Brother Of the Regulator of Imprinted Sites (BORIS), which is frequently overexpressed in cancers." (PMID 23745176, 2013). "Herein we examined the methylation status of this site, including parental origin, and show that this novel consensus sequence binds to CTCF and mechanistically functions as an insulator element in ovarian cancer cells." (PMID 23745176, 2013). "Collectively, RPL35A regulated ovarian cancer progression through CTCF in vitro and in vivo." (PMID 38436544, 2024). "In addition, GEO database analysis showed that CTCF was highly expressed in ovarian cancer (p < 0.001)." (PMID 38436544, 2024). "Consistently, RPL35A regulated ovarian cancer progression depending on CTCF in vitro and in vivo." (PMID 38436544, 2024). "Consistently, our data revealed that CTCF knockdown could partially reverse the regulation of RPL35A overexpression on ovarian cancer cells." (PMID 38436544, 2024). "Therefore, the mechanism of RPL35A and CTCF regulating ovarian cancer progression required to be further explored." (PMID 38436544, 2024). "This suggested that binding of CTCF could directly regulate gene expression in ovarian cancer cells." (PMID 28977939, 2017). "These suggest that binding of CTCF in ovarian cancer cells could directly regulate a series of metastasis-associated genes." (PMID 28977939, 2017). "Our results suggest that CTCF could be a novel drug target to treat ovarian cancer by interfering with cancer cell metastasis." (PMID 28977939, 2017).
ovarian carcinoma (continued). "Our objective was to investigate whether CTCF plays a crucial role in epithelial ovarian cancer metastasis." (PMID 28977939, 2017). "In addition, to the best of our knowledge, this study is the first to demonstrate that CTCF knockdown significantly suppressed ovarian cancer cell migration and invasion in vitro and tumor metastasis in vivo." (PMID 28977939, 2017). "Collectively, our data indicate that CTCF may promote ovarian cancer metastasis by broadly regulating a series of metastasis-associated genes." (PMID 28977939, 2017). "Increased expression of CTCF predicts poor prognosis of ovarian cancer patients." (PMID 28977939, 2017). "Additionally, the expression of CTCF was also evaluated by IHC analysis of primary and metastatic lesions from a different cohort comprising 20 epithelial ovarian cancer patients." (PMID 28977939, 2017). "Thus, we suggested that RPL35A regulated ovarian cancer progression depending on CTCF." (PMID 38436544, 2024). "Taken together, these data suggest that CTCF may play a key role in ovarian cancer metastasis." (PMID 28977939, 2017). "However, the expression pattern of CTCF and its roles in ovarian cancer growth and metastasis remain unknown." (PMID 28977939, 2017). "Thus, we hypothesized that CTCF may regulate ovarian cancer metastasis and serve as a prognostic indicator." (PMID 28977939, 2017). "In addition, compared to the control group, the relative input rate of CTCF was increased in HO‐8910 and SK‐OV‐3 cells due to the overexpression of RPL35A (p < 0.001), suggesting that RPL35A could promote the direct binding of transcription factor YY1 to CTCF in ovarian cancer cells." (PMID 38436544, 2024). "Ovarian cancer cells with interfered expression of RPL35A and CTCF were inoculated into nude mice by subcutaneous injection to establish xenograft tumour model." (PMID 38436544, 2024). "Functional tests were performed both in vitro and in vivo in this study to confirm the impact of RPL35A on the advancement of ovarian cancer cells through facilitating the direct interaction between YY1 and CTCF." (PMID 38436544, 2024). "Indeed, our data suggest that CTCF may be an oncogene in epithelial ovarian cancer." (PMID 28977939, 2017). "In conclusion, RPL35A drove ovarian cancer progression by promoting the binding of YY1 and CTCF promoter, and inhibiting this process may be an effective strategy for targeted therapy of this disease." (PMID 38436544, 2024). "Western blot analysis revealed that CTCF protein expression was directly correlated with that of CTBP1 (R=0.69, P<0.01), SERPINE1 (R=0.56, P<0.05) and SRC (R=0.83, P<0.0001) in 18 fresh ovarian cancer specimens." (PMID 28977939, 2017). "In addition, we performed IHC analysis to examine the expression of CTCF and SRC, CTBP1 and SERPINE1 in a different cohort comprising 40 ovarian cancer specimens." (PMID 28977939, 2017). "Indeed, we observed a direct correlation between CTCF and CTBP1, SERPINE1, and SRC expression in cell lines, xenografted tumors and human ovarian cancer specimens." (PMID 28977939, 2017). "First, we found that CTCF expression was increased in ovarian cancer tissues compared to non-tumor tissues." (PMID 28977939, 2017). "We performed qPCR and IHC analyses to examine CTCF expression in epithelial ovarian cancer specimens and paired non-tumor normal tissues from a total of 30 patients." (PMID 28977939, 2017). "In this study, we did not observe any effects of CTCF knockdown on the proliferation of ovarian cancer cells in vitro or in vivo." (PMID 28977939, 2017). "We also performed an in situ proximity ligation assay (ISPLA) in BORIS-positive ovarian cancer cells (OVCAR8) and human testis tissues, confirming that CTCF and BORIS proteins are co-localized in a chromatin context of both cancer and germ cells where the two proteins are co-expressed." (PMID 26268681, 2015).
ovarian carcinoma (continued). "Firstly, we interfered with the expression of RPL35A and CTCF in ovarian cancer cells, and named empty vector (negative control), RPL35A (RPL35A overexpression), shCTCF (knocked down CTCF) and RPL35A + shCTCF (simultaneously upregulated RPL35A and downregulated CTCF)." (PMID 38436544, 2024). "In addition, we observed increased CTCF expression in epithelial ovarian cancer samples (n=57) compared with non-tumor samples (n=12) in a cohort of patients from a GEO database (GSE66957, P=0.009)." (PMID 28977939, 2017).
breast tumors (11 papers, 2008 to 2022). "Consistent with a putative tumor suppressor role, data from the Cancer Genome Atlas (TCGA) reveals that 63% of all breast tumors harbor CTCF copy number loss (CNL)." (PMID 36037342, 2022). "CTCF single allele deletions are prevalent in a majority of breast tumors." (PMID 36037342, 2022). "In the breast tumor cells we observed the loss of CTCF in all regions analyzed." (PMID 22277129, 2012). "Quantitative real-time reverse transcription PCR (qRT-PCR) indicated that the CTCF mRNA level was decreased significantly in human breast tumors (n = 20) compared with peritumoral tissues." (PMID 29212169, 2017). "Interestingly, the association between high SNAI1 expression and low CTCF has also been observed clinically, as we found a significant correlation between low CTCF and high SNAI1 expression in patients’ breast tumors." (PMID 36037342, 2022). "To evaluate the feasibility of this hypothesis, we measured CTCF mRNA levels in the breast tumor-derived cell lines." (PMID 20305816, 2010). "As not only cell cycle inhibitors p16 and p19 are controlled by CTCF, but also c-Myc, pRb, p21 and p27, loss of CTCF function may support cancer formation and indeed, 87.7% of tested breast tumors showed alterations in the ratio between PARylated 180 kDa and 130 kDa forms of CTCF." (PMID 22969794, 2012). "We analysed enhancer-promoter interactions using Chromatin Interaction Analysis by Paired End Tag (ChiA-PET) data for CCCTC-binding factor (CTCF) and DNA polymerase II (Pol2) in MCF7 breast tumour derived cells." (PMID 27600471, 2016). "In order to identify potential target genes, we analysed enhancer-promoter interactions using ChiA-PET data for CCCTC-binding factor (CTCF) and DNA polymerase II (PolII) in MCF-7 breast tumour derived cells." (PMID 27792995, 2016). "ZNF703, CTCF, and GNAS alterations were exclusively observed among HR‐positive/HER2‐negative patients, which was consistent with what was observed in a study on 11 616 breast tumors." (PMID 35971249, 2022). "Interestingly, in normal breast cells, CTCF is distributed along the locus miR-125b1, whereas in primary breast tumors, we observed the absence of this factor." (PMID 22277129, 2012).
colon cancer (11 papers, 2010 to 2025). "In the Caco-2 colon cancer cell line, CTCF and POL2RA has peak calls at the TSS site of PANCR-AS1, confirming the presence of these transcription factors using another data modality." (PMID 41256376, 2025). "We therefore conclude that the binding of CTCF to the intron of the CCAT1 gene endows colon cancer cells with a WNT signaling-dependent growth advantage that efficiently outcompetes a cell population lacking this functional CTCFBS." (PMID 35017527, 2022). "Additionally, many other driver genes are frequently mutated in colon cancer, such as ARID1A, SOX9, FAM123B, BCL9L, RBM10, CTCF, and KLF5." (PMID 34912802, 2021). "In U2OS cells and HCT116 human colon cancer cells, CTCF and Rad 21 promote the recruitment of RNA Pol II to the TERRA promoter region and shRNA-mediated depletion of Rad21 or CTCF results in loss of RNA Pol II binding at the TERRA promoters and consequent decrease in TERRA levels." (PMID 30875900, 2019). "Our analysis revealed that the classical promoter epigenomic mark – H3K4me3, is highly enriched at HMB boundary in normal colon tissue, and the boundaries that are enriched for promoter marks are also enriched for in vivo binding of the insulator protein CTCF in colon cancer." (PMID 26868017, 2016). "As we knew that the transcription factors always had a correlated expression with their downstream genes, thus we used the GEPIA database to explore the expression correlation between GSTM2 and CTCF, RAD21, SP1 in colon cancer." (PMID 36263204, 2022). "The results showed that there were significantly negative expression correlations between the GSTM2 expression with the three transcription factors, which suggested CTCF, RAD21, SP1 as potential transcription factors of GSTM2 in colon cancer." (PMID 36263204, 2022). "At some genomic elements, such as CTCF insulators and non-CpG island (non-CGI) promoters, we found little change between the colon cancer cells (HCT116) and the methylation-deficient derivative cell line (DKO1)." (PMID 25747664, 2015).
gastric cancer (11 papers, 2017 to 2025). A primary or metastatic malignant neoplasm involving the stomach. "Here, we sought to determine whether CTCF was regulated by a signaling pathway or associated with another pathway involved in gastric cancer." (PMID 33665169, 2020). "In gastric cancer, CTCF activates LINC01207 to promotes proliferation, migration, invasion of cancer cells, and inhibits apoptosis through the LINC01207/miR-1301/PODXL axis." (PMID 35070996, 2021). "Gastric cancer patients with a high CTCF mRNA expression had an improved OS compared with counterparts with low CTCF mRNA expression (HR = 0.76, 95% CI = 0.64–0.91, p = 0.0022)." (PMID 30275357, 2018). "Hence, we compared GPR35 and CAPN10 expression fluctuation in kidney and gastric cancer tissues, but also their relationship in kidney cell and gastric cancer cells when knocked out CTCF-bd (binding domain) for CAPN10." (PMID 36333291, 2022).